CD4 (CD4 molecule)
Diseases named in the same sentence as CD4 in open-access papers (continued):
Sharing a sentence is not in itself a finding about the gene and the disease.
Hypertension (continued). "Administration of PGG during Ang II‐dependent hypertension significantly decreased the number of CCR5+CD4+ and CCR5+CD8+ cells." (PMID 30658013, 2019). "Almost 20% of the included patients presented with an IAB (14.71% partial and 4.41% advanced) and its presence was related to age, sex, hypertension, and nadir CD4." (PMID 31622385, 2019). "Especially, CD4+ T cells of humans with hypertension produced higher amounts of IL-17A than normotensive controls." (PMID 31321561, 2019). "Higher CD8 and CD4/CD8 in 25(OH)D-deficient T2DM and hypertension patients suggested a Th1 lymphocyte profile induction." (PMID 29769621, 2018). "For instance, humanized mice in which the murine immune system was replaced by human leukocytes showed greater hypertension after Ang II infusion along with increased infiltration of CD4+ cells in the aorta and kidney." (PMID 29688896, 2018). "This interaction can lead to complications such as Cushing’s syndrome, hypertension and poor CD4 cell count recovery." (PMID 30241519, 2018). "Large prospective studies are recommended to better explore this relationship between hypertension and CD4 count." (PMID 29610680, 2018). "In conclusion, this study uncovers a crucial role of Nox2 in CD4+CD25+FoxP3+ Tregs in regulating Ang II–induced hypertension and cardiac remodeling." (PMID 29688896, 2018). "Data in human hypertension are scarce, however, an increase in circulating interleukin-17A producing CD4+ T cells and both CD4+ and CD8+ T cells that produce interferon-γ were observed in hypertensive patients compared with normotensive controls." (PMID 29758052, 2018). "Fifty-seven participants (28.5%) had hypertension and the median CD4 cell count of this study population was 271 cells/μL (IQR: 130–408)." (PMID 29610680, 2018). "The major novel finding of this study is that the expression of Nox2 in CD4+CD25+FoxP3+ Tregs plays a vital role in their function to orchestrate Ang II–induced hypertension and cardiac remodeling." (PMID 29688896, 2018). "A role for CD4+ T cell subsets, specifically Tregs and Th17 cells and their respective cytokines, have been demonstrated in the pathogenesis of hypertension." (PMID 30239234, 2018). "Similar results were observed regarding another T cell subset, namely, the CD4+IL−17A+, which has a recognized role in contributing to hypertension, vascular dysfunction, and damage." (PMID 29854087, 2018). "Participants with CD4 cell counts ≥ 350 cells/μL were three times more likely to have hypertension than those with CD4 cell counts < 350 cells/μL (OR: 3.07; 95% CI: 1.32–7.16; p = 0.006)." (PMID 29610680, 2018). "Progressive trends (P < 0.05) towards increased CD8 and CD4/CD8 were observed in vitamin-D-deficient T2DM and hypertension patients." (PMID 29769621, 2018). "Despite these limitations, this study reiterates the importance of factors associated with hypertension while investigating the effect of HIV infection and CD4 cell count on hypertension." (PMID 29610680, 2018). "The observed trend was an increasing prevalence of hypertension across increasing BMI and a higher BMI with higher CD4 cell count." (PMID 29610680, 2018). "Here, we investigated the role of Nox2 expressed in CD4+ T cells in the pathophysiology of Ang II–dependent hypertension and cardiovascular remodeling." (PMID 29688896, 2018). "Among HIV-positive individuals, WHO stage 1 or 2 disease and CD4 cell count ≥200 were predictive of hypertension." (PMID 30596667, 2018). "After adjusting for BMI, patients with CD4 count ≥ 350 cells/μl were more likely to have hypertension than those with CD4 count < 350 cells/μl (AOR: 2.50, 95% CI: 1.05–5.93, and p = 0.032)." (PMID 29610680, 2018). "In patients with hypertension, the percentage of cells with CD4, CD8, CD3 and CD19 as well as the CD4/CD8 ratio differed significantly across the various categories of serum 25(OH)D3 concentrations." (PMID 29769621, 2018).
Hypertension (continued). "Nevertheless, we do note that the possibility of participants in our study having developed hypertension when their CD4 cell counts were low does exist but cannot be ascertained given the study design." (PMID 29610680, 2018). "T cells that expand in pathology and promote development of insulin resistance, atherosclerosis, and hypertension include predominantly IFN-γ-producing Th1 (CD4+) and Tc1 (CD8+) cells, producing IFNγ and TNF, and IL-17 producing Th17 cells." (PMID 28838042, 2017). "T-cell function in hypertension was assessed by measuring CD4+ and CD8+ T cells that activated pro-inflammatory cytokine release." (PMID 28910394, 2017). "This evidence demonstrates that CD4+ T cells are the main adaptive immune players in the pathological development of hypertension." (PMID 28910394, 2017). "On admission, 78.1% had an early HIV-stage infection (CDC-stage A), with a median CD4 count of 397.5/mm3, 34.0% had one comorbidity, mainly hypertension." (PMID 28453525, 2017). "CD4+ effector T (Teff) cells play a critical role in cardiovascular disease, including atherosclerosis, hypertension, and heart failure." (PMID 28757677, 2017). "Participants with low CD4+ T-cell count < 350 cells/μL and those with WHO clinical disease stage IV had lower risk for hypertension." (PMID 27872756, 2016). "We observed an inverse association between advanced HIV disease (defined as low CD4+ T-cell count and advanced WHO clinical disease stage) and risk for hypertension." (PMID 27872756, 2016). "Numerous preclinical studies and recent genome-wide association studies (GWAS) support a role for both cytotoxic (CD8+) T cells and Th (CD4+) lymphocytes in human hypertension." (PMID 27795961, 2016). "Her continued studies suggest that CD4+ T cells are also in part responsible for the hypertension following placental ischemia since adoptive transfer of CD4+ T cells from the RUPP rat results in hypertension in a normal pregnant rat." (PMID 26135305, 2015). "Subsequent studies revealed that B cells are important in the mechanism whereby CD4+ T cells isolated from RUPP rats elicit hypertension when adoptively transferred into normal pregnant recipient rats." (PMID 26569331, 2015). "Although during normal pregnancy there is reduced T cell activation, studies suggest in obese pregnancies that activation of CD4+ T cells is an impending mechanism that exacerbates placental ischemia-induced hypertension." (PMID 26569331, 2015). "Findings are in line with large clinical trials, though others have argued that ART, low CD4, and viral load can influence the odds of hypertension." (PMID 25490037, 2014). "Other characteristics that were independently associated with progressive CKD included older age, black race, and hypertension, as well as lower baseline eGFR and lower nadir CD4." (PMID 22911697, 2012). "In the present analysis, the relationship between higher CD4 count and higher prevalence of hypertension was most dramatic among young men while the relationship between CD4 count and hypertension seemed blunted among the older age groups." (PMID 21779407, 2011). "The prevalence of hypertension was 6 times greater among men aged 16–35 years with CD4 greater than 200–350 compared to men with lower CD4 counts (1.4% vs. 7.8%, p = 0.02)." (PMID 21779407, 2011). "In the bivariable logistic regression, age, sex, residence, income, physical activity, alcohol intake, duration of HIV, duration on ART, duration on DTG-based ART, WHO clinical stage, CD4 T-cell count, family history of hypertension, BMI, blood pressure, and WC had p ≤ 0.25." (PMID 40799927, 2025). "Additionally, age, physical activity, current smoking, hypertension, CD4: CD8 ratio pre-ART and the duration treatment with ART were associated with steatosis." (PMID 39426127, 2024).
Hypertension (continued). "Because nadir CD4+ T-cell count was missing in 18 participants and hypertension and hyperlipidemia in 13 participants, follow-up sensitivity analyses were conducted that adjusted for nadir CD4, hypertension and hyperlipidemia to test for any substantive change in results." (PMID 37376619, 2023). "The activation, proliferation, and differentiation of CD4+ T cells are intricately regulated by cellular metabolism, and the use of metabolic modulators has shown potential for benefiting individuals with SLE-associated hypertension." (PMID 38137363, 2023). "HIV-related factors like CD4 count, viremia, and antiretroviral therapy regimen were not consistently associated with prevalent hypertension." (PMID 37182060, 2023). "The decrease in total CD4+ T cells further reduces the number of blood pressure-protective Treg cells and leads to a relative increase in pro-inflammatory cytokines, thereby aggravating hypertension and damage to target organs." (PMID 37143996, 2023). "However, the low access to hypertension screening and access to CD4 testing at ART initiation are of concern." (PMID 37755892, 2023). "In univariable analyses, the risk of CKD diagnosis was associated with older age at baseline, history of type 2 diabetes, hypertension, tubule-interstitial nephritis, gout and urolithiasis at baseline, and time-updated absolute CD4 cell count <200 cells/mm3 (all p ≤ 0.05)." (PMID 36011147, 2022). "Interestingly, in our study, we observed higher numbers of the CD4+ T lymphocyte in individuals with hypertension aged 72.3 ± 5.9 years when compared to the controls." (PMID 35053985, 2022). "Advanced and severe CD4 counts were statistically significant with hypertension." (PMID 36141463, 2022). "Amongst those who died, those who did so within the first year had a lower BMI (21.2 ± 4.7 vs. 23.4 ± 6.3 kg/m2; p = 0.02), baseline CD4 count (141.9 ± 161.3 vs. 188.9 ± 181.5 cells/μL; p = 0.03), and prevalence of hypertension (7% vs. 17%; p = 0.01) compared to those who experienced late mortality." (PMID 35643492, 2022). "Finally, (f) showed that severe CD4 counts had a shorter mean time to develop hypertension compared to the other categories." (PMID 36141463, 2022). "In our analysis of all ART patients, the present study found a significant association between hypertension and CD4 cell counts but not viral load." (PMID 34155234, 2021). "Infusion of CD4+ T cells obtained from preeclamptic women in pregnant rats stimulates the immunoglobulin release from B-cells which in turn increases AT1-AA production while inhibition of B-cells reduces AT1-AA mediated hypertension in these rats." (PMID 34681861, 2021). "It is possible that the presence of hypertension might contribute to decreasing CD4-cell counts in those who are older, though this would require further studies." (PMID 34155234, 2021). "Renal immune cell infiltration may mechanistically contribute to the hypertension in this model, with CD4+ T cells contributing to tissue inflammation in the kidneys by secreting cytokines." (PMID 33527772, 2021). "Other molecules, such as RANTES and CCR5 mediate T cell infiltration in animal models of hypertension and may regulate intramural CD4 T cell trafficking PP." (PMID 34220551, 2021). "HHO-FKNN machine learning model has been established for clear discrimination between severe and non-severe patients and identified several critical indicators, including advanced age, Hypertension, acute liver injury, and CD4 T cells, CD8 T cells, and fatigue." (PMID 34786302, 2021). "After adjustment for factors associated with HAND and/or microalbuminuria (i.e., age, educational level, hypertension, CD4+ T-cell nadir), previously microalbuminuric cases had worse cognitive performances for the information-processing-speed domain than controls." (PMID 31980868, 2020).
Hypertension (continued). "In a previous study, we found that nadir CD4+ and duration of HIV infection was associated with CMV IgG, but not with CMV-specific T-cell responses, and a low nadir CD4+ has been associated with increased risk of hypertension in several studies." (PMID 31929537, 2020). "It has been reported that adverse phosphorylation at Tyr657 by PYK2 represents a master switch of eNOS activity in AngII-induced hypertension and may also explain the vascular dysfunction in the CD4-IL-17Aind/+ mice." (PMID 31396305, 2019). "Among HIV-infected adults with CD4 >200 cells/mm3, 10.7% had either stage 1 or 2 hypertension." (PMID 30735518, 2019). "In addition, we observed a higher prevalence of hypertension among obese participants and adults with CD4 above 200 cells/mm3." (PMID 30735518, 2019). "Combined with previous studies, these findings indicated that CD4+ T cells could participate in a variety of vascular diseases, including AS, hypertension, AAA, and AD, and these vascular diseases have complex relationships with each other." (PMID 30258282, 2018). "Moreover, we found a significant correlation between activated CD4+ T cells and IP-10, in patients presenting with arterial hypertension." (PMID 29997625, 2018). "Black patients had the highest prevalence of patients age 50–64, and were generally sicker than both white and Hispanic patients, having lower CD4 cell counts, higher viral loads, and higher proportions of current smoking, drug use, underweight or obese, hypertension, Hepatitis C, and PTSD." (PMID 29353555, 2018). "Nevertheless, prospective cohorts will be better designs to study this association between CD4 cell count and hypertension as serial blood pressure and CD4 cell count measurements over time will enable us to determine at what CD4 cell count values hypertension is most likely to set in." (PMID 29610680, 2018). "IL-22 is mainly derived from Th22 cell which is the new subset of CD4+ cells, whether Th22/IL-22 affects angiotensin II-induced hypertension is still unknown." (PMID 29358851, 2017). "Furthermore, immune suppression (defined by low CD4+ T-cell count and advanced WHO clinical diseased stage) and history of TB were associated with decreased risk for hypertension." (PMID 27872756, 2016). "The hypertension in this model is accompanied by increased activation of CD4+ T helper cells." (PMID 26569331, 2015). "Current literature suggests that one of the major contributions of T cells to hypertension is through the release of cytokines from CD4+ T (helper) cell subsets that promote local inflammation, which under normal physiological conditions would facilitate removal of foreign pathogens." (PMID 25501574, 2014). "Activated CD4+ T-cells infiltrate the kidney and vascular walls in animal models of hypertension." (PMID 25070128, 2014). "The number of CD4+CD25highFoxp3+ cells represent 1-2% of the total CD4+ circulating cells, which is the most potent suppressor subset of Tregs for the maintenance of immune tolerance and homoeostasis, as related to hypertension during pregnancy." (PMID 25574467, 2014). "However, consistent with other reports, we found independent associations with traditional factors like older age, female sex, high blood pressure, dyslipidemia, alcohol use and higher income, in addition to higher CD4 count and ART duration in unadjusted analysis among the PLHIV." (PMID 37507703, 2023). "While hypertension is associated with increased aortic stiffness independent of aortic wall thickness, we can therefore speculate that CD3+, CD4+, and CD8+ T-cell infiltrates and the resulting fibrotic outcomes are behind the increased ASI and aortic wall thickness in our TAK patients." (PMID 35652080, 2022).
Hypertension (continued). "There are 2 major proinflammatory actions driving hypertensive cardiovascular remodeling and hypertension: leukocyte recruitment into cardiovascular tissues followed by T cell/IL-17–driven inflammation and, simultaneously, a destabilized/reduced antiinflammatory CD4+FoxP3+ Treg/IL-10 response." (PMID 35133978, 2022). "Therefore, this study was designed to evaluate the effect of common comorbidities in older age, including hypertension, on changes in the T cell subpopulation and to determine the direction of changes in CD4/CD8 ratio and CMV infections in the Polish population in those over 60 years of age." (PMID 35053985, 2022). "Results show a significant association between hypertension and CD4 cell counts but not viral load." (PMID 34155234, 2021). "Mice lacking CD4+ cells also lack regulatory T cells (Tregs) which may predispose to aggravated hypertension in these animals." (PMID 33394136, 2021). "Lactobacillus rhamnosus can regulate the levels of intestinal metabolites and CD4+ T-cell-induced inflammation through mTOR, thereby alleviating hypertension development and suggesting a correlation between the gut microbiome and mTOR immune balance in hypertension." (PMID 34888100, 2021). "In this study, we hypothesized that higher CMV-specific CD8+ and CD4+ T-cell responses against CMV-pp65 and CMV-gB, or higher serum CMV IgG, would be associated with higher systolic blood pressure, higher pulse pressure and hypertension in PLHIV." (PMID 31929537, 2020). "However, 7.4% of HIV-infected adults with CD4 ≤200 cells/mm3 had stage 1 or 2 hypertension." (PMID 30735518, 2019). "Nevertheless, the experiments with adoptive transfer of CD4+CD25+ Tregs clearly support the contention that Nox2 deficiency in conventional Tregs increases their suppressive ability and confers protection against Ang II–induced hypertension and cardiac fibrosis." (PMID 29688896, 2018). "The prevalence of hypertension in our study population was significantly higher compared to the general population (53% versus 20%, P < 0.0001) and was associated with known risk factors and not with patients' viral load and CD4 levels." (PMID 29623220, 2018). "PLWH with hypertension had more CD8+ EM senescent cells, while those with osteoporosis had more naïve CD4+, naïve CD8+ and NK CD56bright senescent cells." (PMID 40303366, 2025). "A viral pneumonia severe risk warning model was successfully constructed, including eight parameters: age, bacterial coinfection, CD4+, CD4+/CD8+, multiple lung lobe infiltrations, smoking, hypertension, and hospital admission days." (PMID 38811907, 2024). "The associations between CMV IgG and certain covariates of interest (age, CD4, ART, gender, waist–hip ratio, smoking, hypertension, HbA1c) were individually assessed overall and separately for each study group." (PMID 38790897, 2024). "The real relationship between the excessive expression of OX40 on CD4+CD25+FoxP3+ cells and the severity of changes in the maternal body in the course of pregnancy-induced hypertension certainly requires further research." (PMID 37887878, 2023). "Conversely, HZ infection, male sex, cardiovascular history, hypertension, smoking, injecting drug users (IDU), hepatitis C, and estimated glomerular filtration (eGFR) rate < 60 mL/min/m3 and CD4 count < 200 cells/μL have strongly predicted hemorrhagic stroke." (PMID 37770849, 2023). "The aim of this study was to assess the population of circulating CD4+CD25+FoxP3+ cells and its differentiation in terms of CD134 expression in two forms of hypertension: isolated hypertension developing after the 20th week of pregnancy and pre-eclampsia." (PMID 37887878, 2023). "The aim of this study was to assess the population of circulating CD4+CD25+FoxP3+ cells and its differentiation in terms of OX40 expression in two forms of hypertension: isolated hypertension developing after the 20th week of pregnancy and pre-eclampsia." (PMID 37887878, 2023).